ENSG00000199196
Synonyms: LOC124900343
Gene: Small nucleolar RNA gene on chromosome 13 (34,100,711 to 34,100,838, reverse strand). Ensembl gene ENSG00000199196.
Gene Ontology:
Biological process: RNA processing
Cellular component: nucleolus
Homologues: Paralogues in human: SNORA25B (77% identical), SNORA25 (76% identical).